SMYD3 (SET and MYND domain containing 3)
Diseases named in the same sentence as SMYD3 in open-access papers (continued):
Sharing a sentence is not in itself a finding about the gene and the disease.
cancer (continued). "SMYD3 over-expression has been described especially in cancer types carrying K-Ras mutations and since the k-Ras mutations occur in more than a half of human cancers, the link to SMYD3 is clinically very relevant." (PMID 31935919, 2020). "Previous reports showed increased expression of Smyd3 in multiple cancer types and Smyd3 overexpression could contribute to cancer‐associated phenotypes through diverse mechanisms (Bottino, Peserico, Simone, & Caretti, 2020)." (PMID 32779886, 2020). "Besides cell proliferation, SMYD3 has been linked to the increased migration and invasion ability of cancer cells in several tumor cell lines." (PMID 31935919, 2020). "Although all these reports shed some novel light on the intricate layers contributing to the regulation of SMYD3 levels, the clinical relevance of SMYD3 over-expression in cancer warrants a more comprehensive understanding of the underlying molecular mechanisms." (PMID 31935919, 2020). "SMYD3 has also been implicated in a number of human cancers." (PMID 29856759, 2018). "Poor cancer prognosis is often linked with SMYD3 overexpression." (PMID 27790639, 2016). "We tested this hypothesis by means of transfecting sh-SMYD3 cancer cells with a SMYD3 gene mutated at the either the EEL or the NHSC amino acid sequences of the SET domain." (PMID 25980436, 2015). "However, the mechanism underlying SMYD3‐mediated crosstalk between cancer cells and immune cells and the downstream immune effector molecules of SMYD3 signaling remains unknown." (PMID 40548645, 2025). "In addition, the regulatory association of SMYD3 with HMGA2 could be generalized to a pan-cancer level." (PMID 37237385, 2023). "One major mechanism that SMYD3 displays is that this methyltransferase interacts with one of its catalytic products H3K4me3, as an epigenetic hallmark of active transcription, to potentiate the transcription of several key genes favoring survival and proliferation of cancer cells." (PMID 37386026, 2023). "Of note, as previously referred, we recently found a SMYD3 genetic variant that was predicted to be deleterious, suggesting that, albeit with lower frequency, SMYD3 may also be involved in genetic susceptibility to inherited cancers." (PMID 34503239, 2021). "IPA functional analysis of the repressed genes revealed that many of the genes down-regulated upon SMYD3 knockdown encode cell death/survival and cell proliferation/growth regulators, including those known to be key components of cancer initiation and progression." (PMID 26350217, 2015). "A key mechanism underlying the pro-meiotic effect of SMYD3 inhibition is the significant upregulation of CDC25A, a phosphatase recently shown in cancer cell models to be negatively regulated by SMYD3 through post-translational mechanisms." (PMID 40636673, 2025). "Overall, these data support the important role of SMYD3-dependent c-MYC methylation in cancer stemness." (PMID 40588481, 2025). "To investigate the impact of SMYD3 knock-out on cancer cell behavior in vivo, we monitored tumor growth in a mouse model." (PMID 40588481, 2025). "In this study, we revealed that cancer cell‐intrinsic SMYD3 impaired the response of ccRCC to a PD‐1 inhibitor by affecting the infiltration of immune cells in the tumor microenvironment shaped by immunosuppression." (PMID 40548645, 2025). "The tumor immunosuppressive microenvironment (TIME) plays a very important role in supporting cancer outgrowth and metastasis, yet the effect of SMYD3-SHCBP1 signaling on the TIME is currently unclear." (PMID 40157910, 2025). "This sound evidence about the role of SMYD3 in cancer stemness makes it a promising target for the development of personalized therapies for CRC patients with SMYD3-overexpressing tumors." (PMID 40588481, 2025). "In particular, we found that SMYD3 is located on chromatin, and its pharmacological modulation influences key cancer-related processes." (PMID 40588481, 2025).
cancer (continued). "Here, we characterized the involvement and the mechanism of action of SMYD3 in the intricate network of cancer stemness signaling cascades that regulate the onset, progression, and metastatization of CRC." (PMID 40588481, 2025). "SMYD3-driven CDCP1 expression in cancer cells indirectly reprograms neighboring fibroblasts toward a myofibroblastic, pro-tumor phenotype, bridging nuclear epigenetic control with stromal activation." (PMID 41301830, 2025). "Cg12607106 is annotated to the enhancer region of the SMYD3 gene, which is involved in lipid metabolism and inhibiting proliferation in cancer cells." (PMID 40702573, 2025). "Our observations suggest that there is a clinical relationship between cancer cell‐intrinsic SMYD3 and the inhibitory immune microenvironment of ccRCC." (PMID 40548645, 2025). "Secondly, our research specifically investigated the impact of cancer cell‐intrinsic SMYD3 on the tumor immune microenvironment." (PMID 40548645, 2025). "SMYD3, an epigenetic modifier, plays crucial roles in cancer development and progression, as well as in the regulation of various biological processes in normal cells." (PMID 39482529, 2024). "Based on these data, we carried out an immunohistochemical staining analysis of SMYD3 in 11 patients with gastric (GC) or rectal (RC) cancer treated with neoadjuvant chemotherapy and then subjected to surgical resection." (PMID 38812026, 2024). "We found that restoring the expression of WT SMYD3 reduced cancer cell sensitivity to 5-fluorouracil, irinotecan, and oxaliplatin, resulting in drug tolerance levels comparable to those observed in the parental cell line." (PMID 38812026, 2024). "In cellulo and in vivo models were employed to investigate the role of SMYD3 in cancer chemoresistance." (PMID 38812026, 2024). "Our comprehensive analysis reveals a significant upregulation of SMYD3 in EC patient samples, correlating with cancer progression." (PMID 38191478, 2024). "This approach led to the identification of new SMYD3 interactors involved in processes related to cancer hallmarks." (PMID 38812026, 2024). "The SMYD3 protein is frequently overexpressed in human cancers and has been reported to drive cell cycle progression and cell proliferation, and more recently, maintain genome integrity." (PMID 38540216, 2024). "In these studies, it was found that the overexpression of SMYD3 played a significant role in enhancing the proliferation of cancer cells, whereas its downregulation inhibits cell proliferation." (PMID 38892227, 2024). "Several technologies were used to facilitate compound screening about these novel molecules' binding affinities and inhibition activities with SMYD3 protein; the antitumor activity has been assessed in vitro using various cancer cell lines." (PMID 39286779, 2024). "Collectively, these data suggest that SMYD3 plays a crucial role in cancer resistance to CHT treatments in vivo." (PMID 38812026, 2024). "In this light, based on novel evidence on the role of SMYD3 as a cancer genome keeper, we investigated in depth its involvement in drug resistance mechanisms." (PMID 38812026, 2024). "Recent studies on SMYD3 oncogenic role also revealed that it can be crucial for unperturbed cell division by promoting phase transition and allowing cancer cells to bypass cell cycle arrest signals." (PMID 38812026, 2024). "HSP90 increases SMYD3 activity, which contributes to the transcription of genes that promote cancer cell proliferation." (PMID 39564119, 2024). "Then, to evaluate in vivo the effect of knocking out SMYD3 on cancer cell chemosensitivity, we analyzed tumor growth in mice." (PMID 38812026, 2024). "In many cell types, SMYD3 is located in the cytoplasm, with a fraction of the protein also located in the nucleus in several cancer cells." (PMID 38892227, 2024). "To date, several structures of inhibitors that have been confirmed to target SMYD3 have been identified, and these inhibitors are candidates for cancer therapy." (PMID 39482529, 2024).
cancer (continued). "In particular, research and the development of specific inhibitors for SMYD2 and SMYD3 have demonstrated the potential of targeting these proteins to inhibit the growth and metastasis of various cancers." (PMID 39482529, 2024). "By developing drugs that specifically inhibit SMYD2 and SMYD3, researchers hope to provide new, more effective treatments for cancer patients." (PMID 39482529, 2024). "The histone methyltransferase, SMYD3, is overexpressed in many types of cancer(s) yet is often underexpressed in corresponding normal healthy tissues." (PMID 39286779, 2024). "Functional studies have demonstrated that SMYD3 enhances cancer cell stemness and proliferation in vitro, as well as tumor growth in vivo." (PMID 39482529, 2024). "Nonetheless, our findings portend that other Ras-dependent cancers with increased abundance of SMYD3 are also likely to maintain a feedback loop driving high SMYD levels dependent on persistent activation of MAP3K2/MEK/ERK signaling." (PMID 37976356, 2023). "SMYD3 is a chromatin-modifying oncogene overexpressed in cancer stem cells, where it promotes proliferation, regulates the cell cycle, and mediates immortalization of cancer cells." (PMID 38168272, 2023). "Another methyltransferase inhibitor, SMYD3, has also been clinically tested in several diseases and studied in depth, especially in cancer." (PMID 37220590, 2023). "Protein lysine methyltransferase SET and MYND domain-containing 3 (SMYD3) is aberrantly expressed in various cancer settings." (PMID 37386026, 2023). "The presence of SMYD3 can be used for the diagnosis of cancer, as has been reported for thyroid and small cell lung cancer." (PMID 36838987, 2023). "Since SMYD3 plays critical roles in several cancer types, a few specific inhibitors, such as BCI-121, were developed." (PMID 37386026, 2023). "Subsequently, we performed a qualitative analysis to identify the SMYD3 interactor candidates that were most relevant for their epigenetic role in cancer processes." (PMID 37954147, 2023). "Because of its low abundance in adult somatic tissues, SMYD3 represents a potential therapeutic target in multiple cancer types." (PMID 37976356, 2023). "With regard to the mechanisms responsible for aberrant SMYD3 expression in cancers, several mechanistic models are needed to be proposed at diverse regulatory levels in the future." (PMID 37237385, 2023). "In this study, we confirmed that SMYD3 promoted the propagation in GC cells, which was consistent with the previous findings obtained in other cancer settings." (PMID 37386026, 2023). "Considering the oncogenic functions of MET and the emerging involvement of SMYD3 in GC, here we investigated the role of SMYD3 as a protein partner of MET in this cancer type and elucidated their structural and functional interplay." (PMID 37887325, 2023). "In a previous study, we showed that SMYD3 interacts physically with various crucial players involved in cancer pathways." (PMID 37887325, 2023). "Functional experimental results suggested that SMYD3 enhanced cancer cell stemness and proliferation in vitro and tumor growth in vivo." (PMID 37237385, 2023). "Recently, we identified SMYD3 as an important effector of ten cancer hallmarks based on its direct interaction with ATM, BRCA2, CHK2, MTOR, BLM, MET, AMPK, and p130." (PMID 37954147, 2023). "Our data have extended the characterization of SMYD3 as a MAPK regulator to another cancer type and link its catalytic activity to aggressive, EMT-associated phenotypes of PCa." (PMID 37976356, 2023). "It has been reported that SMYD3 promoted tumor proliferation and metastasis by potentiating specific genes transcription in many cancers." (PMID 36057625, 2022). "In particular, we focused on tripeptide distribution and characterized the biological function of each identified protein to find the most relevant SMYD3 interactor candidates involved in cancer hallmarks." (PMID 35495117, 2022).
cancer (continued). "To gain further insight into the role played by SMYD3 in cancer, we investigated in depth the interaction between SMYD3 and specific P-proteins identified in our screening that are involved in pathways related to cancer hallmarks." (PMID 35495117, 2022). "In the current study, we performed a comprehensive in silico analysis of all protein sequences identified by screening the whole human proteome for our previously tested tripeptides in order to gain insight into novel SMYD3 cancer-related roles." (PMID 35495117, 2022). "By identifying new SMYD3 interactors involved in important cancer hallmarks, this study extends the range of potential pathways amenable to co-targeting with this approach." (PMID 35495117, 2022). "Many oncogenes have been demonstrated to be regulated by SMYD3 at the transcriptional level through H3K4me3 modification, highlighting that SMYD3 as an important epigenetic regulator in cancer cells." (PMID 36575438, 2022). "Using these models, we find that genetic depletion or pharmacologic inhibition of SMYD3 sensitizes cancer cells to alkylating therapeutics." (PMID 35819319, 2022). "SMYD3 can be considered a versatile player that can activate all three stress response stages to promote cancer cell survival." (PMID 35495117, 2022). "Of note, in vivo studies on RAS-driven formation of PC and lung adenocarcinoma demonstrated that SMYD3 is a critical effector in cancer progression." (PMID 35495117, 2022). "In this context, overexpression of SMYD3 actively participates in cancer progression by synergizing with the RAS–ERK oncogenic pathway through MAP3K2 methylation." (PMID 35819319, 2022). "Surprisingly, this computational analysis allowed us to identify in silico various critical players implicated in cancer processes, such as mTOR, BLM, MET, AMPK, and p130 (RBL2), as novel SMYD3 interactors." (PMID 35495117, 2022). "In recent years, in-depth knowledge of SMYD3-mediated cancer activity was accelerated by the efforts from academic groups and pharmacological companies to develop novel and more efficient SMYD3 inhibitors." (PMID 35495117, 2022). "We used publicly available data (Broad Institute and NCI's Cancer Target Discovery and Development Network), which revealed that SMYD3 expression levels correlate with increased resistance to CP (Pearson correlation coefficient ρ = 0.48)." (PMID 35819319, 2022). "Recent data from our group are consistent with the crucial role played by SLiMs in the PPI network of SET and MYND domain containing 3 (SMYD3) in different cancer study models, including BC, CRC, and other gastrointestinal tumors." (PMID 36496998, 2022). "It has been shown that overexpression of SMYD3 in different cancers is correlated to severe clinical implications in the patients, with significant reduction of overall survival and with accelerated disease progression towards more aggressive stages." (PMID 36520265, 2022). "Our study sheds light on a novel role of SMYD3 in cancer, uncovering this enzyme as a mediator of alkylation damage sensitivity and providing a rationale for small-molecule SMYD3 inhibition to improve responses to established chemotherapy." (PMID 35819319, 2022). "In particular, to gain insight into the oncogenic role of SMYD3, we clustered in silico the 8,650 P-proteins based on their involvement in the ten hallmarks of cancer." (PMID 35495117, 2022). "Among these 28 P-proteins, we focused on the Bloom syndrome protein (BLM) as a putative SMYD3 interactor because of its involvement in cancer." (PMID 35495117, 2022). "The cross-talk between SMYD3 and its novel interactors can be contextualized by discriminating early, middle, and late SMYD3-dependent molecular events in cancer cell adaptive stress response leading to cell survival and cancer progression." (PMID 35495117, 2022). "Nonetheless, SMYD3 specific activity in cancer development and progression is currently under debate." (PMID 35495117, 2022).
cancer (continued). "Next, we confirmed high SMYD3 protein expression in SCLC using IHC staining of human cancer biopsies." (PMID 35819319, 2022). "Our findings, which are consistent with previous research, indicated that RAB32, SMYD3, AP2M1, and HSP90B1 were associated with cancer progression." (PMID 35610596, 2022). "In this scenario, the direct and indirect involvement of SMYD3 in various cancer-related processes appears straightforward." (PMID 35495117, 2022). "This novel SMYD3 function is crucial for sustaining tumor progression since cancer cells need to repair DNA damage to continue to proliferate." (PMID 34503239, 2021). "In this review, we dissect the emerging role played by SMYD3 in the regulation of cell cycle and DNA damage response by promoting homologous recombination (HR) repair and hence cancer cell genomic stability." (PMID 34503239, 2021). "SMYD3 functions have been mainly studied in different cancer cell lines, where it promotes proliferation and invasion." (PMID 34069776, 2021). "As referred above, SMYD3 involvement in cancer cell growth has been called into question based on compelling evidence showing that SMYD3 is dispensable for autonomous cell proliferation." (PMID 34503239, 2021). "Over the past decade, most of the reports aimed at investigating SMYD3 function in cancer focused on the effect of its overexpression on cell cycle progression." (PMID 34503239, 2021). "Targeting SMYD3 and its function in the initiation and progression of cancer would support the discovery of anti-cancer drugs." (PMID 34281237, 2021). "SMYD3 was also reported to stimulate homologous recombination (HR)-related genes to modulate DNA repair in many cancer cell lines." (PMID 34201935, 2021). "While much of the literature as well as the scope of this paper is focused on the role of SMYD3 in cancer, SMYD3 has been shown to be critical in cardiac and skeletal muscle development." (PMID 33637115, 2021). "Mechanistically, the authors showed that SMYD3 directly binds and upregulates WNT10B, a component of the Wnt/Beta-catenin pathway which is a commonly mutated pathway in many cancer types." (PMID 33637115, 2021). "As such, efforts should be made to gain a better understanding of the role of SMYD3 in cancer cell cycle progression." (PMID 34503239, 2021). "Knockdown of SMYD3 has been reported to decrease cell proliferation in a wide variety of cancers, while its overexpression promotes cell growth, transformation and reduces apoptosis sensitivity." (PMID 34503239, 2021). "SMYD3 was originally described as an H3K4 methyltransferase that regulates the transcriptional activities of downstream genes involved in cancer progression." (PMID 34301921, 2021). "The role of SMYD3 role in malignant proliferation, migration, invasion, and progression has been extensively studied in many cancer types." (PMID 33637115, 2021). "Overexpression of SMYD3 plays an important role in the proliferation, adhesion, invasion, and migration of cancer cells, whereas decreases in SMYD3 expression inhibit cell growth, migration, invasion, and apoptosis." (PMID 34301921, 2021). "Reported roles of SMYD3 in cancer include the following: epithelial-mesenchymal transition, cell cycle alteration, promotion of cell proliferation, increased telomerase activity, and cell immortalization." (PMID 33637115, 2021). "SMYD3 contributes to the restoration of damaged DNA in cancer cells and therefore enables unperturbed cell division." (PMID 34503239, 2021). "Due to these important roles, targeting the methyltransferase activity of SMYD3 has been suggested to be a promising strategy for developing anti-cancer drugs." (PMID 34281237, 2021). "This suggests the potential involvement of SMYD3 in the S/G2 checkpoint and hence in cell cycle deregulation, one of the critical steps in cancer development." (PMID 34503239, 2021).